CRP (C-reactive protein)
Diseases named in the same sentence as CRP in open-access papers (continued):
Sharing a sentence is not in itself a finding about the gene and the disease.
Hypertension (continued). "Therefore, we included studies reporting data on participants diagnosed with hypertension or high blood pressure, defined as SBP over 130 mmHg and DBP higher than 80 mmHg, and reporting on exercise or physical fitness and CRP levels." (PMID 39246645, 2024). "Based on the size of the RERI estimate, the synergy between periodontitis status and CRP levels was more prominent in the participants aged ≥ 60 years (RERI, 1.30; 95% CI, 0.40–2.53) and those with hypertension (RERI, 0.76; 95% CI, -0.21 to 1.97) than that in the total population." (PMID 39453923, 2024). "For CAD prevention (no-CCS patients, with arterial hypertension/diabetes melitus/hypercholesterolemia), the hs-CRP level and AUER can also help determine which interventions are appropriate." (PMID 39064476, 2024). "GDF-15 blood levels were proposed to be a clinically relevant biomarker within the context of MetS, as they have been associated with several MetS components, such as hyperglycemia, hypertension, and hyperlipidemia, high waist circumference, WHR and CRP, and low HDL-C." (PMID 38255954, 2024). "CRP and ESR, respectively, were significantly elevated in obese patients with HS (P < .001 and P < .001), those with hypertension (P < .001 and P < .01), elevated triglycerides (P < .001 and P < .01), low HDL (P < .001 and P < .01), and type 2 diabetes (P < .05 and P < .001)." (PMID 38638915, 2024). "For instance, a study of 196 hypertensive patients over the age of 65 found that the increase in CRP was positively correlated with hypertension in the elderly, though not with the severity of hypertension." (PMID 38791032, 2024). "Moreover, the link between high-sensitivity C-reactive protein (hs-CRP) levels and the development of hypertension (HT) indicates the inflammatory component of HT." (PMID 39597791, 2024). "In their univariate analysis for predicting functional outcome, the significant variables were: copeptin, CRP, age, female sex, NIHSS, hypertension, atrial fibrillation, total anterior circulation syndrome, posterior circulation syndrome and small vessel occlusive." (PMID 39777314, 2024). "Tai Chi, as a traditional Chinese exercise, has fewer side effects, lowers lipids, lowers glucose, lowers C-reactive protein (CRP) and other inflammatory factor concentrations, and is useful in protecting vascular endothelial function and delaying the onset of hypertension." (PMID 38373214, 2024). "In addition to stratification factors, we adjusted for age, CRP, eGFR, sex, HDL-c, LDL-c, UA, CLD, PLT, Cystatin C, hypertension, HBA1C, DM, CKD, smoking, and drinking status." (PMID 38402161, 2024). "With the occurrence of PCAD (0 = no, 1 = yes) as the dependent variable, we included sex, BMI, smoking history, drinking history, hypertension, Hcy, Scr, FIB, FBG, hs-CRP and AIP as the independent variables in the binary logistic multivariate regression analysis model." (PMID 39107719, 2024). "Several risk factors associated with T2DM include genetic predisposition, unhealthy diet, physical inactivity, cardiovascular disease (CVD), dyslipidemia (DLP), hypertension (HTN), high C-reactive protein (CRP), depression, watching TV, smoking, and air pollution." (PMID 39062722, 2024). "The exclusion criteria for this systematic review include studies that do not focus on individuals with high blood pressure, report CRP levels, or provide data on exercise or physical fitness." (PMID 39246645, 2024). "In addition, higher age and CREA, as well as lower hypertension incidence rate, WBC, D-dimer, cTnI, NT-proBNP and CRP were found in the type B group compared with the type A group." (PMID 38188253, 2023). "In this sense, a longitudinal study on type 1 diabetes showed that higher levels of VCAM-1 (but not E-selectin or C-reactive protein) at baseline and through the 20-year follow-up period predicted the prevalence and incidence of hypertension." (PMID 37513556, 2023).
Hypertension (continued). "In the LVH group, the male ratio, age, BMI, hypertension stage 2 ratio, creatinine, UA, Hcy, and CRP were all considerably greater than those in the non-LVH group, although the HDL-C was significantly lower." (PMID 36816384, 2023). "Patients with HAPR were less likely to have arterial hypertension and hypercholesterolemia and had lower body mass index, lower glomerular filtration rate and higher levels of C-reactive protein compared with patients without HAPR." (PMID 36786829, 2023). "There were no clear differences in the effects when it came to analyses by hypertension or CRP (results not shown) among seniors in any of the exposures." (PMID 38455908, 2023). "The CKD group had significantly higher body mass index (BMI), HOMA-IR, serum total cholesterol (TC), TGs, low-density lipoprotein cholesterol (LDL-C), C-reactive protein (CRP), liver CAP, and prevalences of liver steatosis and history of hypertension, but a significantly lower eGFR (all P < 0.05)." (PMID 37400794, 2023). "Furthermore, the RDW was positively correlated with CRP in children with hypertension, suggesting that inflammation plays a role in the pathogenesis of LVH and RDW elevation in children with hypertension." (PMID 36816384, 2023). "In the non-diabetic group, patients with high hs-CRP were more likely to have smoking, hypertension, ACS, CKD, and higher concentrations of lipid profile." (PMID 37081535, 2023). "Increases in IL-6 and hs-CRP predict incidence of hypertension in older individuals without cardiovascular disease." (PMID 37324636, 2023). "Given the nature of those factors (e.g., waist-to-hip ratio, SBP, DBP, CRP, HDL, and a history of metabolic disease or hypertension medication), it is assumed that suboptimal cardiovascular, metabolic, and immune systems may increase the risk of breast cancer." (PMID 38115125, 2023). "OPG levels significantly correlate with insulin resistance, C-reactive protein (CRP), IL-1, PDGF, and TNF-α levels but do not correlate with common CV risk factors: hypertension, dyslipidemia, or abdominal obesity." (PMID 36834544, 2023). "In the subgroup analysis stratified by gender, race/ethnicity, smoking, high blood pressure, the negative correlation of albumin with CRP was remained." (PMID 37653773, 2023). "In the first model, when adjusted for hypertension, GFR, the presence of unilateral or bilateral PAD, and serum CRP tertiles, the odds ratio conferred by serum Cys C in the upper tertile was 6.57 (2.10–20.47), and Cys C remained a significant independent determinant of low ABI (p = 0.016) (Model 1)." (PMID 35453881, 2022). "P values for interactions were > 0.05 for all of the subgroups, suggesting that the increased risk of all-cause mortality associated with sTfR was clear regardless of age, DM, hypertension, CKD, cancer, anaemia, iron deficiency, and CRP." (PMID 35831434, 2022). "Patients of the external cohort were older and had a higher prevalence of hypertension, higher BUN and CRP levels, a higher body temperature, higher calculated and expected A-a O2 gradients, lower arterial oxygen saturation, and a lower Horowitz index than patients in the development cohort." (PMID 35160331, 2022). "The analysis was adjusted for insulin, metformin, anti-hypertensive treatment, drinking, smoking, BMI, hypertension, diabetic duration, age, gender, ALT, AST, GGT, WBC, NEU, LYM, NLR, hs-CRP, FFA, TC, TG, HDL-C, LDL-C, Urea, Cr, HbA1c, FPG, 2hPG, GA, GA/ALB, UA and eGFR." (PMID 35842724, 2022). "Last but not least, no measures of inflammatory proteins such as CRP or IL-6 were used in the analysis, and clinical conditions such as hypertension and type 2 diabetes should be further explored." (PMID 36713451, 2022). "In addition, they had a higher prevalence of CVD, hypertension, and cancer; more daily intake of folic acids from food; and higher HbA1c, insulin, HOMA-IR, fasting glucose, and CRP levels; and lower blood vitamin B12 and eGFR levels." (PMID 35548409, 2022).
Hypertension (continued). "By comparing the mild with the severe group, it was found that there was a significant correlation between disease severity and patients' age, hypertension, coronary heart disease, history of cerebral infarction, modified Fisher score, WBC, neutrophils, CRP, and CLR (P < 0.05)." (PMID 35769371, 2022). "There was a significant increase of C-reactive protein in women with preeclampsia (p < 0.003) compared to pregnant women without hypertension." (PMID 36034841, 2022). "However, there were no statistical difference in other factors including drinking, atrial fibrillation, anticoagulants, family history of hypertension, mDBP, FBG, and CRP between groups (P > 0.05)." (PMID 35677332, 2022). "In addition, the fatty liver, hypertension, preoperative oxygenation impairment, and a higher level of DBP, neutrophile (NE), and C reactive protein (CRP) were more common in excessive BMI groups (all p < 0.05)." (PMID 36465611, 2022). "In OSA patients with hypertension, OA did not affect circulating inflammatory marker levels (white blood cells count, CRP, IL-6, IL-10, and TNF-a)." (PMID 35866792, 2022). "Compared with the coexistence of low CRP and non-hypertension, the prevalence of high CRP levels along with simultaneous hypertension was noted to be more common among females at baseline." (PMID 36262245, 2022). "In the cohort, 4,462 (45.4%) had both normal CRP levels and non-hypertension, 785 (8.0%) had elevated-CRP levels alone, 3,592 (36.6%) had hypertension alone, and 982 (10.0%) had both the two conditions." (PMID 36262245, 2022). "Multivariable Cox regression analyses (covariates: demographics, CRP, smoking, T2D, hypertension, dyslipidemia, HDL-C, renal function) did not reveal significant associations between one log unit increase in TMAO concentrations and risk of MACE." (PMID 35807835, 2022). "Furthermore, Cys C kept its significance as a predictor of severe PAD after adjustments for hypertension, estimated GFR, unilateral- or bilateral PAD, and CRP in a logistic regression model." (PMID 35453881, 2022). "In our study, we observed that the coexistence of diseases such as ischemic heart disease, hypertension and type 2 diabetes resulted in higher concentrations of suPAR and CRP in patients in comparison to those not affected by these diseases." (PMID 35330458, 2022). "Individuals with high CRP levels had a higher prevalence of hypertension, regardless of their troponin test result." (PMID 35566579, 2022). "Additionally, a significant relationship between increased CRP, MMP-9, and MMP-2 levels and systolic hypertension and arterial stiffness was demonstrated." (PMID 35873099, 2022). "Both CRP and SAA were higher in the hypertension group until 10 days after admission." (PMID 33580165, 2021). "Post-operatively, cfPWV showed a stronger correlation with age, HR and CRP and was no longer significantly associated with sex, MAP, hypertension or eGFR." (PMID 34957246, 2021). "Patients with hypertension exhibited statistically significantly higher CRP levels compared to those without hypertension (5.1 ± 11.7 vs. 3.7 ± 10.1, p < 0.001, OR = 1.009 (1.005–1.012))." (PMID 33419028, 2021). "Among women with incident hypertension living in rural Senegal, DBS CRP, a biomarker of chronic inflammation, was significantly associated with SBP change over a 1-year period; while DBS MDA, a biomarker of acute oxidative stress, was significantly associated with concurrent SBP levels." (PMID 34943129, 2021). "The increased expression of C-reactive protein (CRP) and interleukin-6 (IL-6), two important circulating markers of inflammation, were found after sleep deprivation, and has been shown to predict cardiovascular events, hypertension and type two diabetes." (PMID 33479186, 2021).
Hypertension (continued). "ssociations were essentially not modified by further adjustment for current depressive episode, antidepressant use, history of CVD, hypertension, B vitamins (PLP, riboflavin) and low-grade inflammation (composite score of CRP, SAA, sICAM-1, IL-6, IL-8 and TNF-α)." (PMID 34409496, 2021). "We were able to predict gout in our patient population using four biomarkers (serum uric acid, CRP, sex, and arterial hypertension) with a predictive value of 0.70 and rule out OA (negative predictive value of 0.92) and CPPD (negative predictive value 0.77)." (PMID 34063875, 2021). "In the univariate analysis, PS ≥ 2, hypertension, heart disease, upper GC, CEA ≥ 5, CA19-9 ≥ 37, albumin< 3.5, CRP ≥ 0.5, pT4, pN+, positive lymphatic invasion, positive venous invasion, Neut ≥ 3690, Lymp < 1860, Plt ≥ 27.2 × 104, and SII ≥ 395 correlated with poor OS." (PMID 34118953, 2021). "Second, the two groups were not completely homogeneous, differing in male sex incidence, arterial hypertension rate and serum CRP values; however, none of these values was used as criteria for decision making during the intensivist consultation." (PMID 34843531, 2021). "In this retrospective observational study, a negative correlation between CLC and initial GI involvement was found, independent of age, gender, CRP, albumin globulin ratio, hypertension, and dyspnea." (PMID 33526973, 2021). "Testing the dependency of the variables used for stratification using Chi-squared test, we obtained that being older or younger than 70 years is related with sex (p < 0.0001), HBP (high blood pressure) (p < 0.0001), SaO2 < 90% (p < 0.0001), LDH < 677 U/L (p = 0.0004) and CRP < 131 mg/L (p = 0.0023)." (PMID 34315437, 2021). "The highest tertile of cystain C was associated with the high proportions of men, smoking, lack of physical activity, hyperglycemia, hypertriglyceridemia, hypertension, low HDL cholesterol, and high mean values of age, fasting insulin, hs-CRP, carotid IMT-mean, and IMT-maximum." (PMID 33129312, 2020). "Compared with deaths without hypertension, CRP and LDH increased, and CD4+ cells and CD8+ cells decreased significantly in deaths complicated with hypertension." (PMID 33009426, 2020). "The results of Kaplan-Meier survival curves with log-rank test showed that venerable age (≥60 years old), comorbidity, hypertension, lymphopenia, hypoalbuminemia, elevated NLR and CRP could obstruct the recovery and discharge of patients." (PMID 33110593, 2020). "Age, pre-existing conditions (cardiac disease, hypertension, and more than two comorbidities), and 1st Laboratory detection (WBC, NEU, LYM%, NEU%, NLR, FIB, CRP, TBIL, ALB, GRF, CK-MB, Myoglobin, and Troponin) were identified as the predictors of the severity of disease by univariate analysis." (PMID 32582575, 2020). "In a study conducted in Iceland in 2009 (n = 758), hypertension had a negative effect on FVC, while hypertension and high CRP were independent and additive determinants of FEV1." (PMID 33076466, 2020). "In the multivariate analysis adjusted for hypertension, female sex, previous stroke, pre-stroke cognitive decline, the use of anti-depressant before stroke, and the NPI score, CRP level remained the independent predictor of depression (OR: 2.23, 95%CI: 1.28–3.90, P < 0.01)." (PMID 31996746, 2020). "The 8 patient variables independently associated with study outcomes included: fever for more than 5 days, Arterial Hypertension, Pulmonary ultrasound pattern (“wet” or “dry”), P/F index, Lactates, withe blood cells count (WBC), C-reactive protein (CRP) and Age." (PMID 32930963, 2020). "Age, CRP, HbA1c, FPG, LDL-C, BMI, TG, SUA, SBP, and DBP were significantly higher in hypertension than those in the normotension, whereas, eGFR level were lower in hypertension than that in the normotension." (PMID 32293295, 2020).
Hypertension (continued). "Subjects who developed hypertension were significantly heavier and had higher systolic and diastolic BP, hs-CRP levels, and IL-1β levels at baseline than did subjects who did not develop hypertension during the mean follow-up of 2 years." (PMID 32292598, 2020). "Additionally, when the age, gender, history of smoking, hypertension and type 2 diabetes, the serum concentration of CK, LDH, CRP and ESR were adjusted, the adjusted hazard ratio for serum 25(OH)D was 0.730 (95% confidence interval 0.578-0.992, P = 0.008)." (PMID 32167486, 2020). "In general, among the patients with hypertension combined with CHF with preserved LVEF, the level of proinflammatory status indicators (CRP, TNF-α, IL-6) corresponded to the normative range of values; however, it was significantly higher in males than in females." (PMID 35366254, 2020). "It has been reported that CRP reduces NO produced by endothelial cells, upregulates the expression of AT1R, and downregulates the expression of AT2R, influencing the RAAS and contributing to hypertension." (PMID 30984420, 2019). "Statistically significant increase in the levels of resistin, CRP and TLC was seen in patients of hypertension (group B), stable angina pectoris with hypertension (group C) and myocardial infarction with hypertension (group D) as compared to normal subjects of group A (p < 0.001 for all)." (PMID 31258568, 2019). "The remaining factors CRE, BUN, and CRP did not contribute to the association between SUA and hypertension (ME: P > 0.05)." (PMID 31215428, 2019). "Higher baseline levels of CRP in older healthy women have been shown to predict the subsequent development of hypertension and CV events in both hypertensive and non-hypertensive postmenopausal women." (PMID 31287027, 2019). "In patients with essential hypertension, the four-week treatment with lecardipine increased the number of endothelial progenitor cells and reduced levels of interleukin (IL)-18, Monocyte chemoattractant protein 1 (MCP-1), and CRP compared to placebo." (PMID 31337127, 2019). "Additionally, the treatment with Angiotensin II receptor blockade reduces the levels of CRP, TNFα, IL-6, and MCP-1 in patients with essential hypertension." (PMID 30935055, 2019). "The previous study used a binary outcome for hypertension, which would not detect a non-linear relationship between CRP and BP." (PMID 29855349, 2018). "Both SNPs genotypes were not significantly related to hypertension or to IL-6 and CRP plasma levels." (PMID 29495593, 2018). "Age, gender, race, smoking, DM, hypertension,previous AMI, smoking, HDL, BMI, CRP." (PMID 30281693, 2018). "Indeed, in recent years, inflammation and endothelial dysfunction, as expressed by levels of C-reactive protein (CRP) and cellular adhesion molecules (CAMs), have been proposed as putative determinants of arterial stiffness/pulse pressure and hypertension." (PMID 29101422, 2018). "In the patients with cancer, only the CRP concentration was associated with the BNP levels independent of the age, creatinine level, hypertension, body mass index, and the medication status (p<0.01)." (PMID 28570595, 2017). "Neither a history of smoking or hypertension nor levels of IgE, white blood cells (WBC), or C-reactive protein (CRP) showed a significant association with risk." (PMID 28978347, 2017). "In the present study we investigated the predictive value of standard serum markers as well as clinical markers, including C-reactive protein (CRP), Neutrophil to Lymphocyte ratio (NLR) and early hypertension (eHTN) in an unselected prospective patient population treated with sunitinib for mRCC." (PMID 28859644, 2017). "Higher grade of hypertension and hypertensive TOD had higher CMV IgG antibody and CRP levels." (PMID 28837559, 2017). "Slight elevations of CRP are seen in several conditions that are not inflammatory, such as hypertension, consumption of the Western diet, and arterial stiffening." (PMID 29435395, 2017).